BMPR2 (bone morphogenetic protein receptor type 2)
Diseases named in the same sentence as BMPR2 in open-access papers (continued):
Sharing a sentence is not in itself a finding about the gene and the disease.
Obesity (continued). "In conclusion, our data on expression, genetics as well as evolutionary aspects suggest a role of BMPR2 in the pathophysiology of obesity and provide some evidence for thrifty genotype hypothesis." (PMID 21311592, 2011). "Also our recent studies on BMPR1A, partner in the receptor complex with BMPR2, suggest a regulatory role of these receptors in obesity." (PMID 21311592, 2011). "However, little is known about the role of BMPR2 in the pathophysiology of human obesity despite evidence for involvement of BMPs in the regulation of adipogenesis." (PMID 21311592, 2011). "Furthermore, miR-6402 can serve as a novel therapeutic agent for obesity and its associated metabolic complications by targeting Bmpr2 as a signalling regulator of adipogenesis, rather than commonly studied adipogenesis markers such as Pparg." (PMID 40028748, 2025). "We hypothesized that BMPR2 might have a role in the pathophysiology of obesity." (PMID 21311592, 2011). "Consistent with recent studies on BMPR1A, positive correlation of BMPR2 mRNA expression with obesity suggests that obese individuals may have enhanced BMP-2/4 signalling, which may stimulate adipose tissue differentiation thereby contributing to increased fat mass." (PMID 21311592, 2011). "In the present study, we identified miR-6402 as a novel obesity regulator that targets Bmpr2 and inhibits BMP4/BMPR2-induced adipogenesis." (PMID 40028748, 2025). "Similarly, some DEGs of the COPD dataset, like the regulator of BMPR2 pathway and APELA, are also the obesity-related genes." (PMID 37886639, 2023). "In addition, from the results of PPI network of obesity and COPD, the hub genes in COPD-PPI had close relationship with BMPR2." (PMID 37886639, 2023). "BMPR2, a serine threonine kinase located on chromosome 2q33-q34, is responsible for the trans-phosphorylation of BMPR1, further suggesting BMPR2 as candidate gene for obesity." (PMID 21311592, 2011).
hereditary hemorrhagic telangiectasia (10 papers, 2016 to 2022). A disorder of angiogenesis leading to arteriovenous dilatations: cutaneo-mucosal hemorrhagic telangiectasias and visceral shunting. "Following the identification of BMPR2 haploinsufficiency as a molecular mechanism of disease, additional causal variants were described in genes encoding the ALK1 (ACVRL1) and Endoglin (ENG) receptors, which have been observed in association with hereditary haemorrhagic telangiectasia (HHT)." (PMID 35772304, 2022). "That is, hereditary hemorrhagic telangiectasia (or HHT) caused by mutations in ACVRL1 and ENG, involves arteriovenous malformations mainly affecting the lungs and liver; or, mutations in BMPR2 may lead to pulmonary hypertension with no impairment of the endothelium in other organs." (PMID 35163400, 2022).
gastric cancer (9 papers, 2016 to 2025). A primary or metastatic malignant neoplasm involving the stomach. "For example, Peng and colleagues found that miR-100 suppressed the proliferation and induced apoptosis of gastric cancer cells by targeting BMPR2." (PMID 34337085, 2021). "Examples of such escape include the mutation of SMAD4 in pancreatic ductal adenocarcinoma (PDAC) and gastric cancer (GC), the TβR I mutation in colon cancer, and even mutations in genes that encode TGF-β ligands (BMP5), receptors (TβR II, AVCR2A, BMPR2), and SMADs (SMAD2 and SMAD4)." (PMID 35461253, 2022). "MiR-100-3p has been shown to control the proliferation and the apoptosis of human gastric cancer cells via binding to bone morphogenic protein type 2 receptor (BMPR2), and it may be involved in producing interleukin (IL)-8 and IL-1β in mesangial cells." (PMID 34046405, 2021). "The most specific loci were in the exons of genes JAK1 and CHD3 (for endometrial cancer); BMPR2, ELAV3, GLYR1, and ZNF43 (for colon cancer); and XYLT2 (for stomach cancer)." (PMID 37894432, 2023).
lung carcinoma (9 papers, 2009 to 2024). "MDA-MB-468 cells demonstrated less BMPR2 expression on the plasma membrane and JL5 caused significantly less trafficking of BMPR2 from the plasma membrane to the cytoplasm in comparison to sensitive lung cancer cell lines." (PMID 34563224, 2021). "We used JL189 a selective inhibitor of BMPR2 to determine if BMP inhibition altered expression of TCA cycle intermediates in lung cancer cell lines." (PMID 39315260, 2024). "BMPR2 signaling promotes anabolic metabolism in lung cancer cells and C. elegans by activating PI3K/Akt/mTOR signaling." (PMID 39315260, 2024). "By Western blot analysis, there was equivalent expression of BMPR2 between the lung cancer cell lines and MDA-MB-468 cells." (PMID 34563224, 2021). "In the present study, we show that Ym155 significantly suppresses BMP signaling and mislocalization of BMPR2 in lung cancer cell lines and MDA-MB-468 cells." (PMID 34563224, 2021). "Using the JL5 resistant MDA-MD-468 cell line and sensitive lung cancer cell lines, we examined the effects of BMPR2 inhibition on BMPR2 mislocalization to the cytoplasm, microtubule destabilization, lysosome activation and cell survival." (PMID 34563224, 2021). "We show that inhibition of BMPR2 signaling destabilizes microtubules in sensitive lung cancer cells." (PMID 34563224, 2021). "We reported that JL5 induces the mislocalization of BMPR2 to the cytosol in lung cancers cells and decrease BMPR2 signaling." (PMID 34563224, 2021). "When BMPR2 activity was inhibited with JL5, Ym155, or siRNA knockdown of BMPR2, lysosomal activity was increased in lung cancer cells as demonstrated by an increase in lysosome acidification, LAMP1 expression, and Cathepsin B activity." (PMID 34563224, 2021). "We examined if insulin regulated BMPR2 in lung cancer cells." (PMID 35641992, 2022). "By Western blot analysis, lung cancer cell lines express BMPR2." (PMID 35641992, 2022). "The microtubule-destabilizing chemotherapeutic agent Vinblastine produced a response similar to that of BMPR2 inhibition with an increase in lysosome acidification, cytosol localization, and increase in Cathepsin B activity in lung cancer cells and MDA-MB-468 cells." (PMID 34563224, 2021). "Our studies in lung cancer cells and C. elegans are consistent with BMP signaling activating PI3K and downstream anabolic signaling pathways Akt and mTOR by BMPR2 Smad-independent mechanisms." (PMID 35641992, 2022). "Chloroquine together with VAD also prevented the decrease in expression of BMPR2 at the plasma following JL5 and Ym155 treatment in lung cancer cells." (PMID 34563224, 2021). "For example, BMPR2, BRD7, PRKAG2, PRKAR1A and PPP2R2A (PP2A Bα subunit B55α), which are differentially expressed between group V (H+V−S+[M/T]) and groups II/IV (H+V+S−/H+V−S+[M]), play roles in tobacco-mediated lung diseases and lung cancers." (PMID 35642061, 2022). "During starvation BMPR2 expression is decreased and lung cancer cells were no longer responsive to BMP2 ligand." (PMID 35641992, 2022). "MDA-MB-468 cells have few cells that expressed BMPR2 at the plasma membrane and JL5 did not cause mislocalization of BMPR2 to the cytoplasm or lysosome, which occurs in sensitive lung cancer cells." (PMID 34563224, 2021). "Furthermore, BMPR2 is overexpressed in the majority of human lung carcinomas independent of cell type." (PMID 19463170, 2009).
lung fibrosis (9 papers, 2017 to 2025). "Given the strong clinical association between PAH and lung fibrosis, understanding BMPs/BMPR2-mediated signaling pathway is important for development of therapeutic strategies to treat IPF." (PMID 39142248, 2024). "The impact of BMP receptors, in particular BMPR2, on pulmonary fibrosis is growing attraction to researchers." (PMID 39142248, 2024). "The study also indicated that miR-215 was upregulated in herbicide-induced pulmonary fibrosis (in vitro and in vivo) causing the activation of the TGF-β pathway by inhibiting the expression of the BMPR2 target gene." (PMID 38085380, 2023). "The current study also showed a significant reduction in BMPR2 in BLM-induced pulmonary fibrosis and was restored in IKBM mice indicating a NF-κB-mediated regulation." (PMID 35083615, 2022). "Next, we examined the gene and protein expression of Rfx2, one of three common upregulated genes among the three combinations of nintedanib- and vehicle-treated mice based on progression of pulmonary fibrosis (Rfx2, Hspa1a, and Hspa1b), and Bmpr2." (PMID 35714115, 2022). "In lung fibrosis, reduced expression or dysfunction of BMPR2 has been observed." (PMID 38673961, 2024). "Elevated IL-6 and STAT3 may correlate with the reduction of BMPR2 through upregulation of certain microRNAs (miRs) in the setting of lung fibrosis." (PMID 39142248, 2024). "How nintedanib upregulates Bmpr2 during the development of lung fibrosis remains to be investigated; however, we speculate that nintedanib may alleviate lung fibrosis through BMPR2 enhancement." (PMID 35714115, 2022). "miR-215 could aggravate PQ-induced pulmonary fibrosis via repressing BMPR2." (PMID 38532482, 2024). "Bmpr2 may be involved in the development of pulmonary fibrosis in the alveolar region." (PMID 35714115, 2022). "Previous studies have revealed that BMPR2 and ALK3 signaling protects against kidney, pancreatic, and lung fibrosis, supporting our conclusions." (PMID 40125634, 2025). "Intravenously injected MSC-Exos attenuated pulmonary vascular remodeling and lung fibrosis by down-regulating the gene expression of β-catenin, cyclin D1 and TGF-β1 and by enhancing expression of Wnt5a and BMPR2 (Bone Morphogenetic Protein Receptor Type 2)." (PMID 38673961, 2024).
colorectal cancer (8 papers, 2011 to 2025). A primary or metastatic malignant neoplasm that affects the colon or rectum. "•We report 3 cases of breast and colorectal cancer in women with BMPR2-related PAH, all diagnosed at younger-than-expected ages." (PMID 40923964, 2025). "They further illustrated that there was a direct association between LIMK and BMPR2, and Smad4-independent BMP signaling activated the Rho/ROCK/LIMK pathway in colorectal cancer cells." (PMID 25501832, 2014). "Inactivation of BMPR1A, BMPR2, and SMAD4 was frequently observed in sporadic colorectal cancer, correlating to loss of Smad1/5/8 phosphorylation." (PMID 22072987, 2011). "In colorectal cancer, BMPR2 acts as a tumor suppressor gene." (PMID 40923964, 2025). "In the HMF colorectal cancers, we discovered eight predictive gene deficiency models (MSH3, SMC2, SMC6, BMPR2, CLASP2, SRCAP, UBR5, and UVRAG) of monoallelic LOF with PR-AUC-E ranging from 0.21 (CLASP2) to 0.62 (MSH3) (AUROC ranging from 0.68 for SRCAP deficiency to 0.94 for MSH3 deficiency)." (PMID 36883553, 2023). "Differences in expression between carcinoma and normal mucosa, or differential miRNA expression by genotype, was associated with six SNPs, SMAD3 rs12708492, BMPR2 rs228545, and NFκB1 rs230510, SMAD3 rs2414937, NFκB1 rs3821958, and RUNX3 rs6672420 for colorectal cancer overall." (PMID 28061442, 2017). "Additionally, ACVR1B is commonly mutated in pancreatic cancer, and in a majority of sporadic colorectal cancers BMPR2 expression is impaired." (PMID 26447543, 2015).
osteosarcoma (8 papers, 2015 to 2022). A usually aggressive malignant bone-forming mesenchymal neoplasm, predominantly affecting adolescents and young adults. "Studies have shown that BMPR2 is highly expressed in most osteosarcoma tissues, is associated with overall survival in osteosarcoma patients, and promotes invasion and metastasis via the RhoA-ROCK-LIMK2 pathway in human osteosarcoma cells." (PMID 34903128, 2021). "In addition, other molecules which have been found to be associated with osteosarcoma pathogenesis are bone morphogenetic protein type II receptor (BMPR2) and high mobility group box1 (HMGB1)." (PMID 27058531, 2016). "BMPR2 is considered an oncogene in some tumors, including chondrosarcoma, osteosarcoma, and gastric cancer." (PMID 35570745, 2022). "We found that miR-200a targets BMPR2 expression, and overexpression of BMPR2 reverses the effects of miR-200a expression on radiosensitization and induction of apoptosis in osteosarcoma cells." (PMID 34903128, 2021). "The results of qRT-PCR showed that the expression level of BMPR2 was significantly higher and the expression level of miR-200a was significantly lower in osteosarcoma tissues after radiotherapy than that before radiotherapy (P < 0.05)." (PMID 34903128, 2021). "We observed the expression levels of BMPR2 and miR-200a in osteosarcoma tissues and cell lines before and after radiotherapy, and further studied the effects of miR-200a and BMPR2 on the sensitivity of osteosarcoma cells to radiotherapy." (PMID 34903128, 2021). "Compared with 2 Gy+si-NC group, 2 Gy+si-BMPR2 group had significantly lower osteosarcoma cell viability and higher death rate (P < 0.05)." (PMID 34903128, 2021). "Overexpression of BMPR2 reverses the effects of miR-200a on radiosensitization, proliferation inhibition, and apoptosis in osteosarcoma cells." (PMID 34903128, 2021). "Through a previous literature search, it was found that the BMPR2 has been shown to be related to the invasion and metastasis of human osteosarcoma cells." (PMID 34903128, 2021). "The expression of BMPR2 was high and the expression of miR-200a was low in osteosarcoma tissues after radiotherapy and in osteosarcoma cells after irradiation." (PMID 34903128, 2021). "The relationship between BMPR2 expression and osteosarcoma patients’ survival was investigated by bioinformatics and clinical data." (PMID 28938584, 2017). "Here, we demonstrated that BMPR2 expression was elevated in a majority of osteosarcoma tissues compared with normal bone tissue." (PMID 28938584, 2017). "Immunohistochemistry detection of BMPR2 was performed on 67 osteosarcoma samples, which was divided into a high and low expression group according to the cut-off value (median staining score: 4.0)." (PMID 28938584, 2017). "Although the abnormal expression of BMPR2 has been detected in several cancers, research on BMPR2 expression and the osteosarcoma metastatic mechanism is sparse." (PMID 28938584, 2017). "Our data revealed that BMPR2 level, advanced Enneking stage and lung metastasis were correlated with the metastasis-free and overall survival of osteosarcoma patients." (PMID 28938584, 2017). "Mechanistically, we found that LIM domain kinase 2 (LIMK2) was phosphorylated and activated by BMPR2 and that this event was crucial for activation of the BMPR2-mediated signal pathway in osteosarcoma cells." (PMID 28938584, 2017). "Further, BMPR2 mRNA was increased in osteosarcoma and was correlated with metastasis in osteosarcoma." (PMID 28938584, 2017). "The role of BMPR2 in human osteosarcoma cell migration, invasion and metastasis was examined in vitro and in vivo." (PMID 28938584, 2017). "To investigate the relationship between BMPR2 levels and the outcomes in osteosarcoma, we first searched for publically available datasets." (PMID 28938584, 2017). "The changes in cell motility and invasion suggest a pro-metastasis role for BMPR2 in osteosarcoma cells." (PMID 28938584, 2017).
osteosarcoma (continued). "We systematically investigated the role of BMPR2 in osteosarcoma cell lines, human tissue samples and xenograft models." (PMID 28938584, 2017). "Endogenous BMPR2 mRNA and protein levels were examined in six osteosarcoma cell lines, among which HOS, KHOS, 143B, MNNG cell lines showed significantly higher levels of BMPR2 mRNA and protein than U2OS cells." (PMID 28938584, 2017). "Given that invasive capacity in BMPR2 has been found at both the tissue and cell levels, study of the role and mechanism of BMPR2 in osteosarcoma metastasis has important clinical value." (PMID 28938584, 2017). "In this study, BMPR2 expression was found markedly elevated in osteosarcoma and this expression correlated with reduced overall and metastasis-free survival." (PMID 28938584, 2017). "In order to explore whether miR-200a affects the radiosensitivity of osteosarcoma cells by regulating BMPR2, and to provide new targets and new ideas for radiotherapy of osteosarcoma cells." (PMID 34903128, 2021). "Our results suggest that BMPR2 is overexpressed in radiation-treated osteosarcoma tissue and radiation-irradiated osteosarcoma cells, interfering with BMPR2 expression inhibits osteosarcoma cell proliferation, promotes apoptosis, and increases cell radiosensitivity." (PMID 34903128, 2021). "The results showed that BMPR2 could increase the radiosensitivity of osteosarcoma cells, inhibit cell survival and promote apoptosis." (PMID 34903128, 2021). "This suggests that miR-200a may influence the proliferation, apoptosis, and radiosensitivity of osteosarcoma cells by modulating BMPR2." (PMID 34903128, 2021). "The mechanism may be related to the regulation of BMPR2, which may provide new targets and new ideas for osteosarcoma treatment." (PMID 34903128, 2021). "BMPR2 promoted human osteosarcoma cell invasion and metastasis through the RhoA-Rocklimk2 pathway." (PMID 31889906, 2019). "Moreover, BMPR2-depletion decreased osteosarcoma cell invasion and metastasis in vitro and in vivo by the inactivation of the RhoA/ROCK/LIMK2 pathway." (PMID 28938584, 2017). "This suggests that the altered expression of BMPR2 could significantly affect cytoskeletal rearrangement in osteosarcoma cells." (PMID 28938584, 2017). "We further detected BMPR2 protein expression in 12 osteosarcoma tissues and 12 normal bone tissues by western blotting, and found that compared to normal bone tissue, BMPR2 expression was significantly higher in osteosarcoma." (PMID 28938584, 2017). "Our results highlighted BMPR2 as an invasion and pro-metastasis indicator in osteosarcoma." (PMID 28938584, 2017). "However, from analysis of BMPR2 mRNA levels and the clinical data, BMPR2 overexpression was correlated with metastases in osteosarcoma." (PMID 28938584, 2017). "For the first time, we showed that BMPR2 was a positive regulator of LIMK2 in osteosarcoma cells." (PMID 28938584, 2017). "Osteosarcoma patients with greater BMPR2 expressing level showed a poor overall survival." (PMID 28938584, 2017). "Overexpression of miR-200a inhibits osteosarcoma cell proliferation, promotes apoptosis, and increases cellular radiosensitivity, its mechanism may be involved in the regulation of BMPR2, and may provide new targets and new ideas for radiation therapy of osteosarcoma." (PMID 34903128, 2021). "Furthermore, BMPR2, RGMb, and neogenin were detected in osteosarcoma cell lines by WB." (PMID 30886151, 2019). "However, there is little knowledge about the concrete mechanism of action of BMPR2 in osteosarcoma." (PMID 28938584, 2017). "However, it is unclear whether the effect of miR-200a on the radiosensitivity of osteosarcoma cells and its mechanism is related to BMPR2, and the aim of this study is to investigate whether miR-200a affects the radiosensitivity of osteosarcoma cells by modulating BMPR2." (PMID 34903128, 2021). "BMPR2 (Bone morphogenetic protein receptor 2) is a receptor of BMP and is also highly expressed in osteosarcoma cells." (PMID 34903128, 2021).